BCL2 (BCL2 apoptosis regulator)
Diseases named in the same sentence as BCL2 in open-access papers (continued):
Sharing a sentence is not in itself a finding about the gene and the disease.
neuroblastoma (continued). "In other xenograft models of BCL-2 dependent neuroblastoma, ABT-199 exhibited its effects through inhibition of tumour growth, rather than by inducing apoptosis." (PMID 35568716, 2022). "As we have shown that SK-N-SH cells express high levels of Bcl-2, which have been shown to be important for neuroblastoma survival, we wished to study the effect of combined treatment of HU-585 with anti Bcl-2 compounds." (PMID 35884854, 2022). "While ABT-199 successfully induces apoptosis in high BCL2-expressing neuroblastoma SHSY-5Y cells, BAU-243 triggered autophagic cell death rather than apoptosis in GBM A172 cells, indicated by the upregulation of BECN1, ATG5, and MAP1LC3B expression." (PMID 36309485, 2022). "Less cell growth was possibly due to stronger apoptosis of neuroblastoma cells induced by up-regulated expression of Bax protein and down-regulated expression of Bcl-2 protein." (PMID 36237324, 2022). "The Bcl-2-siRNA (Bcl-2 gene is a key apoptosis inhibitor that is overexpressed in many tumors) carried by this vector can specifically promote apoptosis of Neuroblastoma (NB) tumor cells." (PMID 35194445, 2021). "Subsequent studies have also verified the tumor suppressive impact of miR-34a in the neuroblastoma cells and its inhibitory effects on the expression of BCL2 and MYCN." (PMID 33718173, 2021). "Low NOXA expression is sufficient to cause resistance to BCL-2 inhibition in SCLC and neuroblastoma." (PMID 34065859, 2021). "Bim binding patterns to different pro-survival Bcl2 members determine Bcl2- or Mcl1-mediated apoptosis resistance in neuroblastoma." (PMID 34572875, 2021). "Rutin elicited the intrinsic apoptosis pathway in neuroblastoma cells as shown by the reduced Bcl2 protein and Bcl2/Bax ratio." (PMID 34832851, 2021). "An example of therapy combination has been observed in in vivo neuroblastoma preclinical models with the BCL-2 inhibitor Venetoclax and Fenretinide." (PMID 34630117, 2021). "This studied combination highlighted the use of BCL-2 expression as a biomarker for neuroblastoma patients." (PMID 34630117, 2021). "One target of miR-16 is Bcl-2; miR-186 from peripheral blood NK-derived exosomes has been shown to inhibit proliferation of neuroblastoma cells by targeting TGFβ1 and other proliferation genes." (PMID 34368150, 2021). "Bcl-2 is strongly expressed in most primary tumors and neuroblastoma cell lines, and its expression levels are inversely correlated with the proportion of cells that undergo apoptosis and with the degree of cell differentiation." (PMID 34832966, 2021). "Immunohistochemical characterization showed an intense positive response to Bcl-2 and Bcl-xL in choroid plexus tumors, primitive neuroectodermal tumors (PNETs), and neuroblastomas." (PMID 32260403, 2020). "It has been demonstrated that MYCN-amplified neuroblastoma cells are highly sensitive to BCL2 inhibitors ABT-263 (navitoclax) and ABT-199 (venetoclax)." (PMID 33628735, 2020). "In conclusion, these studies indicate that the antiapoptotic BCL-2 proteins maintain survival of neuroblastoma cells by inhibiting BAK and that treatment with BH3-mimetics released BAK from its antiapoptotic binding partners." (PMID 32203216, 2020). "Here, we provide the first side-by-side comparison of ABT-199, S63845 and A1331852 in neuroblastoma cell lines and primary-derived cultures and find that all three antiapoptotic BCL-2 proteins are relevant therapeutic targets." (PMID 32203216, 2020). "MLN8237 destabilizes N-MYC and synergizes with BCL2/BCLxL inhibitor (venetoclax or navitoclax) to kill MYCN-amplified tumor cells including neuroblastoma and rhabdomyosarcoma." (PMID 33614505, 2020). "Chan and coworkers have also observed that Cu-induced apoptosis is often accompanied by the increased expression levels of Bax and Bak as well as decreased expression level of Bcl-2 in neuroblastoma cells." (PMID 32411316, 2020).
neuroblastoma (continued). "The combination of MCL1 inhibition with ABT-199 displayed efficacy in neuroblastoma with high BCL2 expression in vitro and in vivo." (PMID 32764384, 2020). "Taken together, this study provides the first detailed characterisation of selective BH3-mimetics in neuroblastoma and identifies all three main antiapoptotic BCL-2 proteins as important therapeutic targets." (PMID 32203216, 2020). "In this study, we compared the effects of selective BH3-mimetics in a panel of neuroblastoma cell lines and primary-derived cells, with the aim to assess which antiapoptotic BCL-2 protein is the most important therapeutic target in neuroblastoma." (PMID 32203216, 2020). "The expression of Mcl-1 and Bcl-2 correlated to clinical prognostic factors and survival in neuroblastoma patients." (PMID 30885150, 2019). "Overexpression of BCL-2 was also commonly identified in many childhood solid tumors such as osteosarcoma, glioblastoma multiforme, Wilms’ tumor, and neuroblastoma, highlighting a significant BCL-2 involvement in the development of these cancers." (PMID 31652776, 2019). "In primary cortical neurons and human neuroblastoma cells, GM-CSF acts against programmed cell death and induces BCL-2 and BCL-Xl expressions." (PMID 31920636, 2019). "BCL-2 protein levels varied during differentiation of neuroblastoma cells, with well-differentiated subtypes containing higher BCL-2 expression." (PMID 31652776, 2019). "SLUG has been described as a survival factor in neuroblastoma, lung, and esophageal carcinomas by upregulating Bcl-2, therefore, SLUG can be the transcription factor that linked FAM3B and Bcl-2 increased expression in DU145 cells." (PMID 29357840, 2018). "BCL2 and survivin, two anti-apoptotic proteins, are highly expressed in neuroblastoma wih high level expression correlating with poor prognosis." (PMID 30326621, 2018). "In contrast to patient tumors, the majority of neuroblastoma cells lines have low level BCL2, making inhibition ineffective." (PMID 30326621, 2018). "That being said, the BCL2 inhibitors navitoclax and venetoclax were studied in both in vitro and in vivo models of neuroblastoma with encouraging results in MYCN-amplified cell lines and tumors." (PMID 30326621, 2018). "As also demonstrated in MYCN-amplified neuroblastomas, the susceptible SCLCs died via BIM- mediated apoptosis following disruption of BIM:BCL-2 complexes." (PMID 30234143, 2018). "Previous studies established that neuroblastoma cells are primed to death through sequestration of BIM by either MCL-1 or BCL-2." (PMID 29719597, 2018). "The pro-survival BCL2 proteins BCLXL as well as MCL1 which are both bound by NOXA in neuroblastoma cells inhibit autophagy by sequestration of BECN1." (PMID 28415610, 2017). "Increased expression of MCL1 is a known resistance factor against treatment with BCL2 antagonists in various cancer types, including neuroblastoma." (PMID 28915653, 2017). "The efficacy of BCL2 inhibition has been extensively demonstrated using both in vitro and in vivo model systems of neuroblastoma." (PMID 28915653, 2017). "This promising effect of AITC in controlling JNK/NF-κB/TNF-α cross-linking maintains the Bcl-2 gene family and protects neuroblastoma cells from activated microglia-induced toxicity." (PMID 28671636, 2017). "In conclusion, these data strongly support the further evaluation of dual BCL2/MDM2 targeting as a therapeutic strategy in neuroblastoma." (PMID 28915653, 2017). "BCL2 is an anti-apoptotic member of the BCL2 protein family and is often highly expressed in neuroblastoma tumors." (PMID 28915653, 2017).
neuroblastoma (continued). "In conclusion, these in vivo data confirm our in vitro findings and strongly support further exploration of combined inhibition of MDM2 and BCL2 in the context of neuroblastoma." (PMID 28915653, 2017). "Rhaponticin and rhapontigenin isolated from rhubarb roots (Rhei Rhizoma) significantly inhibit Aβ1–42-induced apoptotic mechanisms by regulating Bax/Bcl-2 proapoptotic genes in human neuroblastoma cells." (PMID 29238386, 2017). "Using data from our large drug screen we predicted, and subsequently demonstrated, that MYCN-amplified neuroblastomas are sensitive to the BCL-2 inhibitor ABT-199." (PMID 26859456, 2016). "Results indicate that the simultaneous inhibition of multiple anti-apoptotic proteins is more effective for treatment of BCL-2-dependent neuroblastoma than inhibition of BCL-2 alone." (PMID 27056887, 2016). "Neuroblastoma cell lines expressing high BCL-2 levels responded better to ABT263 treatment than low BCL-2-expressing cell lines." (PMID 27056887, 2016). "Evaluation of the BCL-2, MCL-1, BCL-XL, BCL-W and BIM protein levels showed significantly higher BCL-2 levels in the sensitive neuroblastoma cell lines CHP126, KCNR and SJNB12 compared with the insensitive cell lines." (PMID 27056887, 2016). "BCL-2 expression was significantly higher in neuroblastoma cells compared with other solid tumor cell lines, and BCL-xL expression was significantly reduced in neuroblastoma cells, resulting in a high BCL-2:BCL-xL ratio." (PMID 26859456, 2016). "We observed that ABT199 treatment of the high BCL-2-expressing neuroblastoma cell lines CHP126, KCNR and SJNB12 indeed resulted in strongly increased MCL-1 levels, while the other anti-apoptotic proteins and the pro-apoptotic protein BIM were not affected." (PMID 27056887, 2016). "Here we provide evidence that this holds true in a highly lethal pediatric solid tumor known to have functional dependence on Bcl-2, neuroblastoma." (PMID 26874859, 2016). "Second, due to high BCL-2/BCL-xL ratios in these cancers, MYCN-amplified neuroblastoma cells retain sensitivity to the BCL-2 inhibitor ABT-199." (PMID 26859456, 2016). "Based on previously performed preclinical studies, the BCL-2 inhibitor ABT263 was considered to have high potential for testing in neuroblastoma patients." (PMID 27056887, 2016). "show that MYCN-amplified neuroblastomas are sensitive to treatment with the BCL-2 inhibitor ABT-199 due to MYCN-driven increase of NOXA." (PMID 26859456, 2016). "Like many tumors, Bcl-2 dependence in neuroblastoma cannot be determined by expression-based methods alone but by a functional determination of Bim:anti-apoptotic Bcl-2 protein binding patterns." (PMID 26874859, 2016). "Of note, BCL-2 protein levels better predict the sensitivity of neuroblastoma cell lines to ABT199 than BCL-2 mRNA levels, as shown by the factor difference in average expression between the sensitive and insensitive cell lines (i.e. ∼14 versus ∼4)." (PMID 27056887, 2016). "First, MYCN-amplified neuroblastoma cells are exquisitely sensitive to the BCL-2/BCL-xL inhibitor ABT-263." (PMID 26859456, 2016). "Although ABT199 induced a strong apoptotic response, comparison of the efficacy of equal doses of ABT199 and ABT263 in mice with KCNR neuroblastoma xenografts expressing high levels of BCL-2 showed superior antitumor activity for ABT263." (PMID 27056887, 2016). "ABT263 furthermore delayed the onset of tumor formation in mice injected with high BCL-2-expressing neuroblastoma cells." (PMID 27056887, 2016). "The anti-apoptotic protein B cell lymphoma/leukaemia 2 (BCL-2) is highly expressed in neuroblastoma and plays an important role in oncogenesis." (PMID 27056887, 2016). "ABT199 treatment of mice with neuroblastoma tumors expressing high BCL-2 levels only resulted in growth inhibition, despite maximum BIM displacement from BCL-2 and the induction of a strong apoptotic response." (PMID 27056887, 2016).
neuroblastoma (continued). "In the current study, we explored the preclinical therapeutic potential of ABT199 for the treatment of BCL-2-dependent neuroblastoma tumors." (PMID 27056887, 2016). "The efficacy of ABT199 was subsequently studied in vivo in mice with high BCL-2-expressing KCNR neuroblastoma xenografts." (PMID 27056887, 2016). "Treatment of the high BCL-2-expressing neuroblastoma cell lines with 62.5 nmol/L ABT199 was already sufficient for almost complete displacement of BIM from BCL-2." (PMID 27056887, 2016). "BCL-2 immunoprecipitation followed by immunoblotting for BIM showed that BIM/BCL-2 complex levels were indeed significantly higher in the sensitive neuroblastoma cell lines." (PMID 27056887, 2016). "Ladostigil has also been shown to act on the prosurvival molecule Bcl-2 and increase the availability of ACh and monoamine neurotransmitters in neuroblastoma SK-N-SH cells." (PMID 26075266, 2015). "Next, we examined the role of H89 pretreatment on the expression of brain-derived neurotrophic factor (BDNF), PSD95, MAP2, and the apoptosis regulators Bcl2 and cleaved caspase-3 in cultured neuroblastoma cells exposed to hypoxia and reperfusion injury." (PMID 26448879, 2015). "Here, we showed that alpha-mangostin decreased caspase-3 activation, decreased Bax mRNA expression, and increased Bcl-2 mRNA expression induced by MPP+ in dopaminergic SH-SY5Y neuroblastoma cells." (PMID 26357513, 2015). "Accumulating evidence indicates that p38 MAPK participates as a modulator in Bcl-2/Bax-mediated apoptosis in neuroblastoma cells." (PMID 25885582, 2015). "In neuroblastoma, hTERT was regulated by miR-138 with an increase of Bax expression and decrease of BCL-2 expression." (PMID 25962180, 2015). "The findings of the present study indicate that melittin suppressed H2O2-induced apoptotic cell death in SH-SY5Y neuroblastoma cells by inducing an increase in the anti-apoptotic enzyme, Bcl-2 and a decrease in pro-apoptotic enzymes, such as Bax and caspase-3." (PMID 25091565, 2014). "BCL2/BAX ratio and expression of BCL2, both were notably reduced in rutin treated neuroblastoma LAN-5 cells." (PMID 25493075, 2014). "The present study confirmed that the protein expression of Cyclin D1, CDK6 and Bcl-2 were reduced by overexpression of miR-34a, which is consistent with previous studies in non-small cell lung cancer A549 cells and neuroblastoma NLF cells." (PMID 25268950, 2014). "MiR-203 leads to G1 phase cell cycle arrest in laryngeal carcinoma cells by directly targeting survivin and miR-210 targets antiapoptotic Bcl-2 expression and mediates hypoxia-induced neuroblastoma cell apoptosis." (PMID 24799764, 2014). "Among the apoptosis-associated genes identified in the microarray was BCL2, an anti-apoptotic gene that is highly expressed in a number of tumor types and associated with MYCN-amplification and unfavorable histology in neuroblastoma." (PMID 24009722, 2013). "Knockdown of BCL2 in neuroblastoma cell lines triggers apoptosis, and ectopic overexpression of BCL2 inhibits apoptosis." (PMID 24009722, 2013). "In this study, we showed that serum deprivation-induced autophagy was accompanied by an up-regulation of total and phosphorylated protein levels of Bcl-2 in neuroblastoma SH-SY5Y cells." (PMID 23658815, 2013). "Recently, miR-204 has been suggested as a novel predictor of outcome in neuroblastoma, functioning, at least in part, by increasing the sensitivity to cisplatin through direct targeting and downregulation of anti-apoptotic BCL2 and TrkB." (PMID 24321270, 2013). "In conclusion, our study demonstrated that rutin plays the antiproliferation of human neuroblastoma cells role through inducing G2/M phase cell cycle arrest and triggering apoptosis; this event is a BCL2-independent process." (PMID 24459422, 2013). "Bcl-2 is highly expressed in a significant percentage of primary neuroblastoma tumors (16-52%), and expression correlates with markers of poor prognosis including MYCN-amplification." (PMID 24009722, 2013).
neuroblastoma (continued). "We assayed changes in BCL2 expression following I-BET726 treatment in a number of neuroblastoma cell lines and observed potent and concentration-dependent suppression of BCL2 in every cell line tested." (PMID 24009722, 2013). "The expression of Bcl-2 was also determined as Bcl-2 has been shown to increase in differentiated neuroblastoma cells." (PMID 23220046, 2013). "BCL2 has also been demonstrated as a direct target of miR-497 in neuroblastoma, although BCL2 knockdown alone only increases apoptosis in a cell line specific manner." (PMID 23531080, 2013). "Except for PUMA, SLUG downregulation facilitates apoptosis induced by pro-apoptotic drugs in neuroblastoma cells by downregulation of Bcl-2 prototypic anti-apoptotic protein." (PMID 23339680, 2013). "Nonetheless, it is clear that the relative contribution of BCL2 silencing to I-BET726 cytotoxicity in neuroblastoma cell lines is variable and, in some cases, has little effect on potency." (PMID 24009722, 2013). "Treatment with GH decreased LDH release, Bax/caspase-3 activity and increased Bcl-2 expression compared with Aβ treatment in a human neuroblastoma cell line." (PMID 23852044, 2013). "In accordance with previous reports, our findings also showed that butein upregulated Bax expression and attenuated Bcl-2 expression in neuroblastoma cells." (PMID 22245810, 2012). "In conclusion, butein-triggered neuroblastoma cells undergo apoptosis via generation of ROS, alteration of the Bcl-2/Bax ratio, and cleavage of pro-caspase 3 and PARP." (PMID 22245810, 2012). "According to that study, Trx is correspondingly upregulated with Bcl-2 downregulation, following transfection of neuroblastoma cells with antisense Bcl-2." (PMID 22654601, 2012). "In the current study, we show for the first time that butein markedly triggers apoptosis in neuroblastoma cells through the generation of reactive oxygen species (ROS), alteration of Bcl-2 and Bax expression, and elevation of pro-caspase 3 activity." (PMID 22245810, 2012). "RhEpo has been shown to induce anti-apoptotic genes including Bcl-xL, Bcl-2, and Mcl-1 in Ewing sarcoma and neuroblastoma cell lines." (PMID 22188703, 2011). "In neuroblastoma cells HCMV induces expression of Bcl-2 resulting in inhibition of apoptosis and chemoresistance, a process that can be reversed by treatment of neuroblastoma cells with the antiviral drug ganciclovir." (PMID 22246171, 2011). "Many antiapoptotic proteins, such as Bcl-2, Mcl-1 and Bcl-XL, have been shown to inhibit chemotherapeutic agent-induced apoptosis in diverse cell system models including hematopoietic and neuroblastoma cells." (PMID 20102612, 2010). "This study shows that in neuroblastoma cell lines overexpressed TF ligated with FVIIa produced upregulation of Bcl-2 expression through the JAK/STAT5 signaling pathway, resulting in resistance to apoptosis." (PMID 18325115, 2008). "Enforced expression of TF in a TF-negative neuroblastoma cell line in the presence of FVIIa induced upregulation of Bcl-2, leading to resistance to doxorubicin." (PMID 18325115, 2008). "Conversely, inhibition of endogenous TF expression in a TF-overexpressing neuroblastoma cell line using siRNA resulted in down-regulation of Bcl-2 and sensitization to doxorubicin-induced apoptosis." (PMID 18325115, 2008). "While expression levels of anti-apoptotic Bcl-2 remained unchanged upon incubation with betulinic acid in neuroblastoma and squamous cell carcinoma cells, an increase in Bcl-2 protein levels was reported in glioblastoma cells." (PMID 19325847, 2008). "Interestingly, hkLAB was found to protect against glutamate-induced apoptosis in neuroblastoma cells by regulating the Bax to Bcl-2 ratio and increasing the expression of antioxidant enzymes." (PMID 40917298, 2025). "In addition, the study is in line with the investigation on the oxygen and glucose deprivation of human neuroblastoma cells concerning the inter-relation of Bax and Bcl-2 levels with astaxanthin." (PMID 40143179, 2025).